ALDH2 (aldehyde dehydrogenase 2 family member)
Diseases named in the same sentence as ALDH2 in open-access papers (continued):
Sharing a sentence is not in itself a finding about the gene and the disease.
acute kidney injury (12 papers, 2021 to 2025). Sudden and sustained deterioration of the kidney function characterized by decreased glomerular filtration rate, increased serum creatinine or oliguria. "A recent study has identified ALDH2 as a critical pathogenic mechanism linked to endogenous lactate accumulation in acute kidney injury and proposes it as a potential therapeutic target." (PMID 41158511, 2025). "In addition, upregulation of ALDH2 can regulate autophagy to protect renal tubular epithelial cells through the Beclin-1 pathway, thereby ameliorating acute kidney injury and neuronal damage caused by hypoxia." (PMID 38609879, 2024). "In a recent study, researchers found that ALDH2 expression is significantly decreased in cisplatin- or maleic acid-induced acute kidney injury (AKI) models, along with mitochondrial dysfunction and tubular epithelial cell apoptosis." (PMID 40968356, 2025). "Several studies investigated the role of ALDH2 in various kidney injuries, showing its protective function in acute kidney injury (AKI) through autophagy-related gene activation." (PMID 39226171, 2024). "Also, aldehyde dehydrogenase 2 (ALDH2) mitigates mitochondrial dysfunction by promoting PGC-1α-mediated biogenesis in acute kidney injury." (PMID 41444219, 2025). "Aldehyde dehydrogenase 2 (ALDH2) is a key enzyme that is involved in alcohol metabolism and mitochondrial oxidative ATP production; however, its function in mitochondrial homoeostasis in acute kidney injury (AKI) is unclear." (PMID 36670098, 2023). "Lactylation of aldehyde dehydrogenase 2 (ALDH2) at lysine 52 (K52la) exacerbates tubular injury and mitochondrial dysfunction in acute kidney injury (AKI), which can be modulated by upregulating SIRT3." (PMID 39737891, 2025). "Studies have demonstrated that CYA can downregulate expression of ALDH2 protein in a rat acute kidney injury (AKI) model induced by cecal ligation and puncture (CLP)." (PMID 35269824, 2022). "However, the role of ALDH2 in acute kidney injury (AKI) remains poorly defined and is therefore the subject of the present study using various cellular and organismal sources." (PMID 34228649, 2021). "As a central component of the cellular defense network against oxidative stress and carbonyl stress, ALDH2’s protective role extends beyond DKD to various pathological conditions, including multiple types of CKD, acute kidney injury, liver fibrosis, and cardiovascular diseases." (PMID 41162187, 2025).
colon cancer (12 papers, 2002 to 2026). "Four studies, all from Japan, have investigated the association between ALDH2 polymorphism and colon cancer risk." (PMID 28253921, 2017). "We observed that cancer of the rectum was more influenced by alcohol consumption than colon cancer, with increased risk among individuals with a ‘weak’ ALDH2 (Glu/Lys) genotype than those with the strongest (Glu/Glu) in terms of enzyme activity." (PMID 12033531, 2002). "Knockdown of ALDH2 expression can significantly suppress the migration of colon cancer cells, while activation of ALDH2 can promote the migration of colon cancer cells." (PMID 38378847, 2024). "pathway in colon cancer and identified ALDH2 and HCDH as potential biomarkers for diagnosing colon cancer and developing new therapeutic strategies." (PMID 38911385, 2024). "ALDH2 exhibited reduced expression in colon cancer tissues obtained from the AOM/DSS-treated mice compared to that in tissue from the saline-treated controls." (PMID 38911385, 2024). "The mRNA levels of both Hadh and Aldh2 were significantly downregulated in colon cancer tissues compared to their adjacent colon tissues." (PMID 38911385, 2024). "Further WB validation with five selected pairs of colon cancer tissues and their adjacent colon tissues also confirmed a significant decrease in ALDH2 expression in tumor tissues." (PMID 38911385, 2024). "The correlation between ALDH2 and PD‐L1 protein expression in eight colon cancer cell lines was also examined by western blot analysis." (PMID 34026438, 2021). "Another murine CT26 colon cancer model was employed to investigate the effect of ALDH2 inhibition on PD‐1 immunotherapy." (PMID 34026438, 2021). "Given that most differentially expressed proteins in the valine, leucine, and isoleucine degradation pathway were downregulated, the expression of HCDH and ALDH2, two key proteins in this pathway, was analyzed in 14 pairs of colon cancer and adjacent colon tissues from 14 patients." (PMID 38911385, 2024). "We validated the downregulation of ALDH2 and HCDH in mRNA and protein level in colon tumor tissues compared to adjacent normal tissues." (PMID 38911385, 2024). "Therefore, ALDH2 and HCDH play crucial roles in the prognosis of patients with cancer and may provide crucial information for the development of immunotherapies for colon cancer." (PMID 38911385, 2024).
gout (12 papers, 2016 to 2025). A condition characterized by painful swelling of the joints, which is caused by deposition of urate crystals. "We evaluated the risk of gout among Taiwanese adults with aldehyde dehydrogenase-2 (ALDH2) rs671 single nucleotide polymorphism (SNP) according to body mass index (BMI) and alcohol drinking." (PMID 33858492, 2021). "In this study, we evaluated ALDH-2 rs671 polymorphism and the risk of gout according to two modifiable factors (BMI and alcohol intake) among Taiwanese adults." (PMID 33858492, 2021). "In summary, our data show that common variants of ADH1B (rs1229984) and ALDH2 (rs671) are independently associated with gout, which indicates that the genotyping of rs1229984 and rs671 can be useful for the evaluation of gout risk." (PMID 28566767, 2017). "The common dysfunctional variant of ALDH2, rs671, also showed a significant association with gout, even after adjustment for alcohol consumption and even in non-drinkers or in drinkers." (PMID 28566767, 2017). "We recently performed a genome-wide association study of gout and a subsequent fine-mapping study which identified rs671 of ALDH2 as a gout locus." (PMID 28566767, 2017). "rs671 (Glu504Lys) of ALDH2 had the most significant association with gout (P = 1.7 × 10−18, odds ratio = 0.53)." (PMID 27181629, 2016). "ALDH2 polymorphisms contribute not only to the metabolism of ethanol and acetaldehyde but also impact predisposition to alcohol-related morbid conditions like hyperuricemia and gout among Asians." (PMID 33858492, 2021). "Rs671 (E504K) of ALDH2 gene was associated with gout in Japanese male and Chinese male populations." (PMID 30123371, 2018). "Thus, we first investigated the association between gout and rs671 of ALDH2 including alcohol consumption in the model." (PMID 28566767, 2017). "Contrary to this expectation, these associations were still significant even after adjustment for alcohol consumption, which indicates that common variants of ADH1B and ALDH2 can be associated with gout susceptibility through not only alcohol consumption but also other factors and/or mechanisms." (PMID 28566767, 2017). "Selection pressure analysis revealed significant enrichment of selection pressure on ABCG2 in addition to ALDH2 loci for all subtypes except for normal type gout." (PMID 32238385, 2020). "Selection pressure analysis revealed significant enrichment of selection for the ABCG2 and ALDH2 loci in Japanese gout patients of each subtype." (PMID 32238385, 2020). "And 11 of the significant variants were from the gout associated loci (GCKR, SLC2A9, ABCG2, CNIH2, MYL2-CUX2 (ALDH2) and BCAS3)." (PMID 28642574, 2017). "Because the sample size of non-drinkers was relatively small, further studies are necessary to clarify the effects of alcohol consumption on the association between gout and common variants of ADH1B and ALDH2." (PMID 28566767, 2017). "Next, we investigated the combined effects on gout of the common variants of ADH1B (rs1229984) and ALDH2 (rs671)." (PMID 28566767, 2017). "Some of the previously reported gout associated loci (except ALDH16A1), including ABCG2, SLC2A9, GCKR, ALDH2 and CNIH2, were replicated." (PMID 28642574, 2017). "The role of both BMI and alcohol drinking in the risk of gout according to ALDH2 rs671 genotypes has not been sufficiently investigated." (PMID 33858492, 2021). "In addition, a recent GWAS found that ABCG2, SLC2A9, ALDH2, and novel loci induce asymptomatic hyperuricemia into gout development." (PMID 33087043, 2020). "Therefore, from the point of view of alcohol consumption, further studies are necessary to be able to elucidate the association between gout and common variants of ADH1B and ALDH2." (PMID 28566767, 2017). "However, the association between gout and common variants of ADH1B has hitherto remained unreported, prompting us to investigate the association between gout and common dysfunctional variants of ADH1B (rs1229984) and ALDH2 (rs671)." (PMID 28566767, 2017).
gout (continued). "Thus, we initially assumed that the associations between gout and common variants of ADH1B and ALDH2 would be accounted for by alcohol consumption." (PMID 28566767, 2017). "In summary, Glu504Lys polymorphism (rs671), a common dysfunctional SNP of ALDH2, is identified as a genuine gout-associated polymorphism in the MYL2-CUX2 locus, and “A” allele (Lys) of rs671 plays a protective role in the development of gout." (PMID 27181629, 2016). "The results revealed that the variants exhibited protective effects against developing gout, namely rs3733589 (SLC2A9), rs3775948 (SLC2A9), rs1014290 (SLC2A9), rs3109823 (ABCG2), rs2622604 (ABCG2), rs6532055 (ABCG2), rs72554040 (ABCG2), rs671 (ALDH2), rs78069066 (MAPKAPK5), and rs77768175 (HECTD4)." (PMID 36221101, 2022). "The involved genes were ABCG2, SLC2A9, PKD2, ZNF518B, ALDH2, HECTD4, and MAPKAPK5 in the phenotype of gout; and only gene SLC2A9 was found in the AH phenotype." (PMID 36221101, 2022). "As expected, analysis including ALDH2 and outside of ABCG2 showed significant enrichment of selection pressure except for normal type gout." (PMID 32238385, 2020). "The results revealed that the Japanese population has evolved to have higher SUA levels, which can result in gout, due to the ABCG2 locus in addition to the already-known ALDH2 gene." (PMID 32238385, 2020). "From ROL type gout, rs4148155 of ABCG2 (pmeta=9.75×10–46; OR=2.79) and rs11066008 of ACAD10 (ALDH2) (pmeta=4.20×10–12; OR=1.79) were revealed to have an association." (PMID 32238385, 2020). "Individuals with and without gout were significantly different based on ALDH2 rs671 genotypes (p-value = 0.0122), alcohol drinking (p-value < 0.0001), and BMI (p-value < 0.0001)." (PMID 33858492, 2021).
melanoma (11 papers, 2015 to 2026). A malignant, usually aggressive tumor composed of atypical, neoplastic melanocytes. "The ALDH2*2 allele is prevalent in East Asians, who have a relatively low incidence of melanoma, and rare in Caucasians, who are at higher risk." (PMID 40558540, 2025). "Because ALDH2 is downregulated in two-thirds of melanoma cells, we knocked out this gene in ALDH2-normal A375 cells to investigate the effects of ALDH2 loss." (PMID 40558540, 2025). "We demonstrate that ALDH2 downregulation in melanoma is associated with increased tumor aggressiveness and resistance to targeted therapy." (PMID 40558540, 2025). "In our global analysis of melanoma datasets, we observed a strong positive correlation between WT ALDH2 and melanoma incidence, while variant alleles showed an inverse relationship." (PMID 40558540, 2025). "All in all, ALDH2 was associated with tumor immune infiltration of immune cells in tumor microenvironment of melanoma." (PMID 38378847, 2024). "ALDH2 was selected as the candidate gene in this research, presenting a high diagnostic and predictive value for melanoma." (PMID 38378847, 2024). "These demonstrate the complexity of the relationship between ALDH2 expression, ALDH2 polymorphism, and melanoma outcomes." (PMID 36831600, 2023). "The ALDH2*2 allele is prevalent in populations with low melanoma incidence, such as Mongolians, but rare in high-risk populations like Caucasians with high alcohol consumption." (PMID 36831600, 2023). "The correlation analysis showed that it was the wild-type ALDH2 allele that was strongly positively correlated with melanoma incidence (R=0.70; P<.001) and mortality (R=0.74; P<.001)." (PMID 35990801, 2021). "Additionally, ALDH2 expression levels in BRAF-mutated metastatic melanoma cells influence cell sensitivity to BRAF and MEK inhibitors, with low ALDH2 expression associated with both intrinsic and acquired resistance." (PMID 40558540, 2025). "After establishing that ALDH2 loss disrupts AcAH detoxification, redox homeostasis, and energy metabolism while promoting inflammation and glycolytic reprogramming in melanoma cells, we next overexpressed this gene in ALDH2-low 1205Lu cells to investigate the effects of its restoration." (PMID 40558540, 2025). "However, the underlying molecular mechanism of ALDH2 in melanoma is still unclear and requires further investigation." (PMID 38378847, 2024). "To understand how genetic risk factors have a role in the observed correlation between alcohol consumption and melanoma incidence/mortality, we examined the correlation of aldehyde dehydrogenase 2 (ALDH2) rs671 polymorphism with both alcohol consumption and melanoma outcomes." (PMID 35990801, 2021). "However, the role of ALDH2 polymorphisms in melanoma remains inconclusive." (PMID 40558540, 2025). "To investigate the significance of ALDH2 downregulation in melanoma biology, we knocked out ALDH2 in ALDH2-normal A375 cells, resulting in a more aggressive tumor phenotype, supporting ALDH2 as a melanoma tumor suppressor." (PMID 40558540, 2025). "In vitro studies showed that ALDH2 overexpression suppresses melanoma cell proliferation, migration, and invasion, suggesting its potential as a therapeutic target." (PMID 40558540, 2025). "While daidzin enhanced AcAH-mediated MAPK activation, Alda-1 pretreatment inhibited activation of all three MAPKs, suggesting that ALDH2 negatively regulates MAPK activation in human melanoma cells." (PMID 40558540, 2025). "In summary, our study highlights the critical role of ALDH2 in melanoma progression and therapy resistance." (PMID 40558540, 2025). "Analysis of the CCLE dataset revealed that among 33 metastatic melanoma cell lines, 70% exhibited low ALDH2 expression, whereas the remaining 30% showed relatively high expression levels." (PMID 40558540, 2025).
melanoma (continued). "Consistently, the majority of CCLE melanoma cell lines exhibited low ALDH2 expression, with 2/3 of metastatic melanoma cell lines showing extremely low or undetectable levels compared to primary melanocytes." (PMID 40558540, 2025). "Having established a correlation between ALDH2 expression levels and drug sensitivity, we next examined ALDH2 expression in melanoma cells with acquired resistance to MAPK/ERK pathway inhibition." (PMID 40558540, 2025). "Together, our findings highlight the importance of ALDH2 in melanoma biology, linking its downregulation to tumor progression, MAPK/ERK activation, metabolic reprogramming, resistance to targeted therapy, and worse patient outcomes." (PMID 40558540, 2025). "Our analysis of multiple melanoma datasets in the Gene Expression Omnibus (GEO) revealed a progressive decrease in ALDH2 expression from normal human skin to primary melanoma and further to metastatic melanoma." (PMID 40558540, 2025). "Given that lower ALDH2 expression correlates with poorer patient outcomes, our findings highlight ALDH2 as a potential prognostic marker and therapeutic target in melanoma management." (PMID 40558540, 2025). "Our findings indicate that ALDH2 downregulation contributes to melanoma progression and therapy resistance in BRAF-mutated human metastatic melanoma cells, highlighting ALDH2 as a potential prognostic marker and therapeutic target in metastatic melanoma." (PMID 40558540, 2025). "ALDH2-KO in A375 melanoma cells resulted in a reduction of both mitochondrial respiration, as measured by OCR, and glycolytic activity, as measured by ECAR." (PMID 40558540, 2025). "In contrast, a small subset of metastatic melanoma cell lines exhibited normal ALDH2 levels (ALDH2-normal)." (PMID 40558540, 2025). "Our present study provides compelling evidence for the functional significance of ALDH2 downregulation in melanoma biology and its impact on tumor progression and therapy resistance." (PMID 40558540, 2025). "Our findings highlight the critical role of ALDH2 as a detoxifying enzyme in melanoma, affecting both targeted therapy response and clinical outcomes." (PMID 40558540, 2025). "Collectively, these findings further indicate that ALDH2 plays a role not only in AcAH detoxification but also in regulating cellular energy metabolism, auto-inflammation, and metabolic reprograming in melanoma cells." (PMID 40558540, 2025). "Analysis of multiple independent GEO datasets confirmed significantly downregulated ALDH2 mRNA expression in melanoma tissues." (PMID 40558540, 2025). "Given the pivotal role of MAPK/ERK signaling in melanoma and cellular response to acetaldehyde, we compared A375 with ALDH2-low SK-MEL-28 and 1205Lu cells." (PMID 40558540, 2025). "Understanding the mechanisms driving ALDH2 downregulation provides new insights into melanoma progression and therapeutic resistance." (PMID 40558540, 2025). "Then we investigated the role of ALDH2 in proliferation, migration, and invasion of melanoma in vitro." (PMID 38378847, 2024). "The immune infiltration analysis demonstrated that the expression of ALDH2 was significantly correlated with the infiltration of the immune cells in melanoma." (PMID 38378847, 2024). "ALDH2 was down-regulated in melanoma, promoting the infiltration levels of immune cells in tumor microenvironment." (PMID 38378847, 2024). "In brief, we identified a key gene biomarker, ALDH2, after comprehensive bioinformatics analysis, which had good specificity and sensitivity to be a biomarker of melanoma." (PMID 38378847, 2024). "ALDH2 had a positive correlation with the infiltrating levels of immune cells in melanoma microenvironment." (PMID 38378847, 2024). "However, the clinical significance of ALDH2 polymorphism in melanoma remains unclear." (PMID 36831600, 2023). "They found that ALDH2 expression was significantly downregulated in 3 Gene Expression Omnibus (GEO) melanoma datasets." (PMID 37297001, 2023).